RUNX2 (RUNX family transcription factor 2)
Diseases named in the same sentence as RUNX2 in open-access papers (continued):
Sharing a sentence is not in itself a finding about the gene and the disease.
melanoma (37 papers, 2007 to 2025). A malignant, usually aggressive tumor composed of atypical, neoplastic melanocytes. "To evaluate RUNX2 association with CXCR4 in melanoma cells, we started by detecting the expression of these two markers and the matrix metalloproteinase 13 (MMP13) invasiveness marker in several melanoma cell lines." (PMID 38474372, 2024). "In summary, this study highlights the association of CXCR4 with RUNX2 expression in melanoma cells and its implications in melanoma invasiveness, osteotropism, and autophagy." (PMID 38474372, 2024). "For instance, a higher expression of the osteogenic master gene RUNX2 has been reported in melanoma cells associated to tumour progression and EMT." (PMID 31781477, 2019). "Here, we extended the analysis of Runt domain of Runx2 in melanoma cells to deepen understanding of the underlying mechanisms." (PMID 31142788, 2019). "Most importantly, we demonstrate for the first time that melanoma cells resistant to the BRAF V600E inhibitor PLX4720 had a significant increase in RUNX2 expression associated with an increase in RTKs expression and activation." (PMID 27102439, 2016). "We have demonstrated that RUNX2-deficient melanoma cells display a significant decrease in three receptor tyrosine kinases, EGFR, IGF-1R and PDGFRβ." (PMID 27102439, 2016). "Thus, the findings of increased autophagy in RUNX2-expressing melanoma cells suggest the association between autophagy and metastatic ability in melanoma." (PMID 38474372, 2024). "In addition to its association with melanoma invasiveness and osteotropism, we also explored the involvement of RUNX2 in autophagy, which is a cellular process associated with bone metastasis." (PMID 38474372, 2024). "Therefore, in order to identify the molecular pathways associated with RUNX2 in melanoma we performed a comparative shotgun proteomic analysis of Runt KO (3G8) and wild-type (A375) melanoma cells." (PMID 31142788, 2019). "In addition, the involvement of RUNX2 in the regulation of four different RTKs implicated in melanoma progression and acquired resistance to BRAF V600E inhibitors suggests that RUNX2 is a potential therapeutic target in patients with melanoma." (PMID 27102439, 2016). "We also implicated RUNX2 as an important factor in melanoma migration and invasion." (PMID 27102439, 2016). "We were the first to demonstrate that RUNX2 was overexpressed in human melanoma cells as compared with normal human melanocytes and that RUNX2 deficiency inhibited cell growth, migration and invasion of human melanoma cells." (PMID 27102439, 2016). "Runx2, in particular, is associated with enhanced TRM cell cytotoxicity and correlates with improved survival in melanoma patients, indicating its relevance for effective local immune surveillance." (PMID 40895552, 2025). "In melanoma, the Runt domain of RUNX2 serves as a critical regulator of neoangiogenesis, driving the formation of new blood vessels." (PMID 40806771, 2025). "First, we compared the levels of two autophagosome markers, microtubule-associated protein 1A/1B-light chain 3 (LC3) and p62, on the MELHO wild-type melanoma cell line and in the three RUNX2 KO cell lines: 1E7, 1B3 and 1F5." (PMID 38474372, 2024). "Recent studies have shown that RUNX2 expression was upregulated in advanced melanomas and correlated with poor patient prognosis." (PMID 38474372, 2024). "In this study, we identified that CXCR4 expression is dependent on RUNX2 in melanoma cells, shedding light on its role in melanoma invasiveness and osteotropism." (PMID 38474372, 2024). "Our data suggest that RUNX2 promotes melanoma progression by upregulating CXCR4, and we identify the latter as a key player in melanoma-related osteotropism." (PMID 38474372, 2024). "In the present study, we used melanoma cells and a RUNX2 knockout (RUNX2-KO) in vitro model to assess the influence of RUNX2 on CXCR4 protein levels along with its effects on markers associated with cell invasion and autophagy." (PMID 38474372, 2024).
melanoma (continued). "RUNX2, a transcription factor related to osteogenesis, has been identified as an important protein involved in melanoma progression." (PMID 38474372, 2024). "We modulated the levels of RUNX2 in melanoma cells and assessed its effects on CXCR4 as well as on markers of cell invasion and autophagy." (PMID 38474372, 2024). "Further research is warranted to fully elucidate the complex interplay between CXCR4, RUNX2, and autophagy in melanoma and develop targeted therapies to improve patient outcomes." (PMID 38474372, 2024). "Our findings shed light on the complex mechanism of RUNX2 in autophagy regulation in melanoma cells." (PMID 38474372, 2024). "To further validate the involvement of RUNX2 in autophagy in melanoma cells, we restored RUNX2 protein levels by transfecting 1F5 RUNX2 KO cells with the pcDNA3/RUNX2 plasmid." (PMID 38474372, 2024). "Our data indicate that the RUNX2 transcription factor promotes the expression of the CXCR4 chemokine receptor on melanoma cells, which in turn promotes autophagy, cell invasiveness, and osteotropism, through the inhibition of the mTOR signalling pathway." (PMID 38474372, 2024). "In contrast to SOX10, RUNX2 can increase the expression of several receptor tyrosine kinases including EGFR in melanoma." (PMID 33916908, 2021). "Particularly, melanoma cells with RUNT-deleted form of RUNX2 have reduced proliferation, increased apoptosis, and reduced EMT." (PMID 34829835, 2021). "Then, we evaluated the metastatic gene expression profile in A375 and RUNX2 RUNT KO (RUNT KO) melanoma cells by using a Human Tumor Metastasis Array." (PMID 32204402, 2020). "Recently, we found that RUNX2 is overexpressed in melanoma cells and its expression is involved in proliferation and migration processes." (PMID 32168858, 2020). "Recently, it has been demonstrated that RUNX2, an important osteogenic transcription factor which is overexpressed in thyroid cancer, promotes melanoma cells’ migration and invasion." (PMID 32168858, 2020). "In summary, our findings, including reduced osteopontin, bone sialoprotein and CD44, supported RUNX2 involvement in promoting melanoma cell osteotropism." (PMID 32204402, 2020). "RUNX2 activity reduction due to inhibition of AKT or ERK signaling decreased PTHrP production in melanoma cells in turn." (PMID 32204402, 2020). "RUNX2 involvement in regulating the epithelial–mesenchymal transition (EMT) process has been demonstrated in melanoma." (PMID 32204402, 2020). "On the basis of our findings, we concluded that the RUNX2 RUNT domain is involved in the mechanisms promoting bone metastasis of melanoma cells via complex interactions between multiple players involved in bone remodeling." (PMID 32204402, 2020). "RUNX2, a master osteogenic transcript ion factor, is overexpressed in several cancer cells; in melanoma it promotes cells migration and invasion as well as neoangiogenesis." (PMID 32168858, 2020). "Recently, we demonstrated that the RUNT domain, namely the RUNX2 DNA binding domain, is involved in different pathways leading to melanoma transformation." (PMID 32204402, 2020). "In the present study, we have investigated the effects of BEL β-trefoil against RUNX2- expressing melanoma cells in vivo by using a xenotransplant model of zebrafish." (PMID 32168858, 2020). "Our previous study showed BEL β-trefoil effects on transcription factor RUNX2 downregulation as well as on the migration ability in melanoma cells treated in vitro." (PMID 32168858, 2020). "Several studies demonstrated the involvement of RUNX2, the master transcription factor of osteogenic differentiation, in the development of melanoma." (PMID 32204402, 2020).
melanoma (continued). "In order to evaluate the role of BEL β-trefoil in affecting the spreading ability of RUNX2 melanoma cells, we used the in vivo model zebrafish." (PMID 32168858, 2020). "To reveal signalling pathways and interaction networks perturbed by inhibition of Runx2 DNA-binding function, we performed a bioinformatics analysis on the proteins whose expression significantly changed between A375 and 3G8 melanoma cells." (PMID 31142788, 2019). "Our approach provides a comprehensive view of molecular details that depend on Runx2 DNA binding function in melanoma cells." (PMID 31142788, 2019). "The bioinformatic interrogation of the SKCM TCGA dataset highlights a strong correlation between the query genes and melanoma (false discovery rate (fdr): 0.000534) and showed that RUNX2 was altered in 9% of subjects affected by melanoma." (PMID 30463392, 2018). "In order to investigate further the role of RUNX2 in melanoma development and to identify a therapeutic target, we applied the CRISPR/Cas9 technique to explore the role of the RUNT domain of RUNX2 in a melanoma cell line." (PMID 30463392, 2018). "All these findings strongly suggest the involvement of the RUNT domain in melanoma metastasis and cell migration and indicate RUNX2 as a prospective target in MM therapy." (PMID 30463392, 2018). "In particular, the regulation of KIT gene by RUNX2 and increased RUNX2 gene expression have been documented in melanoma cells." (PMID 30463392, 2018). "In particular, a higher expression of the osteogenic master gene RUNX2 has been reported in melanoma cells, compared to normal melanocytes." (PMID 30463392, 2018). "Boregowda and colleagues demonstrated that a reduction in Runx2 activity led to decreased growth, migration, and invasion in melanoma cells." (PMID 28264434, 2017). "We initially demonstrated the over-expression of transcriptionally active RUNX2 in melanoma cell lines and melanoma samples as compared with primary melanocytes and melanocytic nevi respectively." (PMID 27102439, 2016). "To further analyze the co-expression of RUNX2 and RTKs, we examined the expression of RTKs in C81-61 and C8161 melanoma cell lines (." (PMID 27102439, 2016). "The metastasis of melanoma to bone was likely caused by high concentrations of TGF-beta and activation of its target genes, including RUNX2." (PMID 27007162, 2016). "We also thank Haiyan Zheng and the Center for Integrative Proteomics Research (Rutgers University, Piscataway NJ) for the Proteomics analysis of ShRNA RUNX2-expressing melanoma cells." (PMID 27102439, 2016). "This conclusion is based on: 1) the down regulation of AXL, EGFR, IGF-1R and PDGFRβ in ShRUNX2 knocked down melanoma cell lines or RUNX2-specific U1 Adaptors-transfected melanoma cells." (PMID 27102439, 2016). "The present study was designed to investigate the relationship between RUNX2 and the expression of receptor tyrosine kinases (RTKs) in melanoma." (PMID 27102439, 2016). "If such a system exists, the regulation of IGF-1R by RUNX2 shown in the present study would suggest the existence of a positive feedback loop of RUNX2/IGF-1/IGF-1R in melanoma cells, promoting melanoma migration and invasion." (PMID 27102439, 2016). "Real time PCR determined that RA2 Adaptor was the most efficient in reducing RUNX2 mRNA levels in both C8161 and 1205LU melanoma cells, lowering RUNX2 mRNA levels to less than 40% of those in the presence of the control NC3wt." (PMID 27102439, 2016). "1205LU melanoma cells exhibited reduced levels of RUNX2 expression at the two time points and a parallel decrease in EGFR and AXL expression." (PMID 27102439, 2016). "In the present study, we examine the role of the transcription factor RUNX2 in the regulation of receptor tyrosine kinase (RTK) expression in melanoma." (PMID 27102439, 2016).
melanoma (continued). "We previously demonstrated that knock down of RUNX2 using RUNX2 shRNA lentiviral expression vectors decreased melanoma cell migration and invasion." (PMID 27102439, 2016). "We previously published the expression of RUNX2 in melanoma cell lines and RUNX2 appeared as a single band on low exposure." (PMID 27102439, 2016). "We also demonstrated that RUNX2 knock down in melanoma cell lines significantly inhibits their migration and invasion potential." (PMID 26204939, 2015). "We also demonstrated that knocking down RUNX2 in human melanoma cells results in decreased levels of the FAK protein and our recent experiments show that RUNX2 regulates FAK mRNA (unpublished results)." (PMID 26204939, 2015). "Lastly, RUNX2 expression was positively correlated with cytokine-cytokine receptor interaction, focal adhesion, and cancer-related pathways, but negatively correlated with melanoma and NK cell-mediated cytotoxicity pathways." (PMID 40703521, 2025). "We previously reported that RUNX2 was involved in melanoma metastasis and cell migration." (PMID 38474372, 2024). "All melanoma cells studied here expressed both RUNX2 and CXCR4 at the mRNA and protein levels." (PMID 38474372, 2024). "Our in vitro data suggest an increase in basal autophagy in melanoma cells expressing RUNX2." (PMID 38474372, 2024). "To verify the role of RUNX2 in promoting autophagy through CXCR4, we used RUNX2 KO melanoma cells." (PMID 38474372, 2024). "We observed that melanoma cells express both RUNX2 and CXCR4." (PMID 38474372, 2024). "Moreover, using melanoma cells KO for the RUNT domain of RUNX2, we demonstrated that the RUNT domain plays an important role in the modulation of the expression of genes involved in bone metastases." (PMID 37199076, 2023). "To evaluate whether FBXW11 has a direct role in the degradation of RUNX2 by the proteasome system, we used a melanoma cellular model in which RUNX2 differs only in the RUNT domain." (PMID 37199076, 2023). "Melanoma leads to the increased proteolytic activity of CAKs, which might be caused by enhanced MAPK pathway activation or RUNX2 elevated level in CAKs." (PMID 36123693, 2022). "Since the first report describing the role of RUNX2 in the differentiation and migration of osteoblasts into chondrocytes and its engagement in the proinvasive/promigratory behaviour of various tumour cells, especially in melanoma cells, RUNX2 has been established as a key factor in metastasis." (PMID 36264762, 2022). "In addition, since the ERK/pERK and AKT/pAKT pathways are associated with both RUNX2 and PTHrP expression, we investigated the modulation of these pathways in WT and RUNT KO melanoma cells." (PMID 32204402, 2020). "Due to the strong link between RUNX2 and skeletal development, we hypothesized that the RUNT domain may be involved in the modulation of mechanisms associated with melanoma bone metastasis." (PMID 32204402, 2020). "Interestingly, we also observed that BEL β-trefoil treatment reduced RUNX2 expression in melanoma cell lines in a dose-dependent fashion." (PMID 32168858, 2020). "Therefore, to better understand the role of this lectin, we investigated the BEL β-trefoil effects in a zebrafish in vivo model, transplanted with human melanoma cells expressing RUNX2." (PMID 32168858, 2020). "RUNX2 is ectopically expressed in melanoma and plays an important role in progression." (PMID 32204402, 2020). "In addition, by using the CRISPR/Cas9 system in the A375 melanoma cell line and by performing the xenotransplantation of KO RUNT melanoma cells in zebrafish, we also found that the RUNX2 Runt domain is involved in melanoma proliferation and migration." (PMID 32168858, 2020). "Accordingly, being aware of the strong association between RUNX2 and bone remodeling agents, we hypothesized that the RUNX2 RUNT domain is involved in mechanisms that promote bone metastasis in melanoma cells." (PMID 32204402, 2020).
melanoma (continued). "Runx2 is a transcription factor involved in melanoma cell migration and proliferation." (PMID 31142788, 2019). "Furthermore, the functionality of the protein with the partially removed RUNT domain was compromised as shown by the observed data, and the malignant features of melanoma cells were restored with the re-expression of WT RUNX2." (PMID 30463392, 2018). "In melanoma, it has been shown that RUNX2 is involved in the regulation of the EMT process." (PMID 30463392, 2018). "By analyzing public databases for recurrent RUNX2 genetic and epigenetic modifications in melanoma, we found that the most common RUNX2 genetic alteration that exists in transcription upregulation is, followed by genomic amplification, nucleotide substitution and multiple changes." (PMID 30463392, 2018). "Some studies have reported also the involvement of the RUNX2 transcription factor in melanoma." (PMID 30463392, 2018). "Therefore, three of the four RTKs that we found negatively regulated in the RUNX2-knocked down 1205LU melanoma cells by mass spectrometry were validated by immunoblot analysis." (PMID 27102439, 2016). "Therefore, we used FAK mRNA as a control for RUNX2 loss of activity and confirmed a reduction of FAK expression in melanoma cells transfected with the selected Adaptors RA2 and RA5 for C8161 cells, and RA2 and RA4 for 1205LU cells." (PMID 27102439, 2016). "We speculate that similar regulation of IGF-1 on RUNX2 expression and activity could exist in melanoma cells, through the activation of IGF-1R and subsequent stimulation of the PI3K and/or the MAPK pathways resulting in RUNX2 positive regulation." (PMID 27102439, 2016). "In addition, melanoma cells with reduced expression of RUNX2 had an increased sensitivity to PLX4720." (PMID 27102439, 2016). "We suggest that RUNX2 may be a driver of increased receptor-tyrosine kinase (RTK)-based autocrine signaling in melanoma and a key player in resistance to targeted therapies involving up regulation of different RTKs." (PMID 27102439, 2016). "This functional interaction led us to hypothesize that AKT activity could also play a role in maintaining RUNX2 levels in melanoma cells." (PMID 27102439, 2016). "We previously showed that RUNX2 regulates the expression of the FAK protein in melanoma cells." (PMID 27102439, 2016). "In addition, we showed that decreased RUNX2 expression was associated with a reduction in the expression of FAK, implicated in cell migration and melanoma metastasis." (PMID 27102439, 2016). "We were interested in analyzing whether reduction of RTK expression resulted in inhibition of phosphorylation of ERK and AKT in RUNX2 knocked down melanoma cell lines." (PMID 27102439, 2016). "This suggests that RUNX2 might play a role in maintaining activation of the PI3K/AKT pathway through the regulation of RTKs in some melanoma cells." (PMID 27102439, 2016). "However, the interplay between CXCR4 and RUNX2 in melanoma cells remains poorly understood." (PMID 38474372, 2024). "We also noticed that transcriptional regulators of EMT including SNAI1, SNAI2, and RUNX2 were present in this list, supporting the hypothesis that the phenotypical plasticity gained through this transdifferentiation process concurs with melanoma aggressiveness." (PMID 37408506, 2023). "Interestingly, VitaminD3, an inhibitor of RUNX2, improved melanoma cells to death by immune cells." (PMID 33413419, 2021). "Thus, Runx2 and Runx3 might act as tumour suppressors in malignant melanoma, and Runx3 in breast, gastric, colon, and hepatocellular carcinomas, as well as non-small cell lung cancer." (PMID 17876328, 2007).